U2AF1 (U2 small nuclear RNA auxiliary factor 1)
Diseases named in the same sentence as U2AF1 in open-access papers (continued):
Sharing a sentence is not in itself a finding about the gene and the disease.
hematological malignancies (18 papers, 2018 to 2025). "Because of recurring somatic mutations in U2AF1 in hematological malignancies, there are increasing interests in the functions of the splicing factor in both physiological and pathological settings." (PMID 38088204, 2024). "Since somatic mutations have been frequently found in ZRSR2 gene in hematological malignancies, there is growing interest in better understanding of the functions of U2AF1-relaed factors in splicing of U2-type and U12-type introns." (PMID 38088204, 2024). "It was also demonstrated that U2AF1 mutations alter 3′ splice site recognition in hematological malignancies." (PMID 36609432, 2023). "Notably, mutation of the other member of the U2AF complex (U2AF1) has been reported in the same hematologic malignancies associated with SF3B1 mutations." (PMID 30867899, 2019). "Previous research has shown that ITP patients harboring mutations in genes such as DNMT3A, TET2, ASXL1, BCOR, PIGA, and U2AF1 tend to progress into other clonal hematologic disorders, leading to treatment ineffectiveness." (PMID 40574285, 2025). "To validate our findings, we analyzed the splicing landscape and expression profiles of key splicing machinery genes, including SRSF2, U2AF1, and ZRSR2, which are known to be frequently mutated in hematological malignancies." (PMID 40158006, 2025). "Mutations in splicing factors, such as U2AF1, SF3B1, SRSF2, ZRSR2, and HNRNPH1, are frequently observed across various hematological malignancies and are associated with poor prognosis and treatment resistance." (PMID 39584923, 2024). "Along with SF3B1 mutations, recurrent missense mutations in U2 small nuclear RNA auxiliary factor 1 (U2AF1) and serine/arginine-rich splicing factor 2 (SRSF2) were discovered in hematological malignancies, and later reported to be present in some solid tumors." (PMID 31634348, 2019). "Notably, mutations in spliceosomal genes such as SF3B1, U2AF1, SRSF2, ZRSR2, and the RNA-stabilizing methyltransferase METTL3 are specifically enriched in haematological disease." (PMID 40495353, 2025). "Relationship between AKT3 and mutations related to MDS or MPN hematological disorders The MDS- or MPN-related mutations affect genes involved in different molecular aspects of gene expression including RNA splicing (SRSF2, U2AF1 and SF3B1), chromatin remodeling (ASXL1) and gene transcription (BCOR)." (PMID 38528080, 2024). "Also, dysregulation in splicing factors, such as the U2AF1 (U2 small nuclear RNA auxiliary factor 1) gene, is related to hematological malignancies." (PMID 36609432, 2023). "In addition, aberrant expression of lncRNAs like HOTTIP, epigenetic like m6A methylation, and transcriptional regulators like SRSF2 and U2 small nuclear RNA auxiliary factor 1 (U2AF1) can lead to abnormally elevated levels of R-loops and ultimately to blood disorders." (PMID 40061014, 2025). "Since, in addition to SF3B1, mutations in U2AF1 and SRSF2 have also been observed in hematological malignancies, UM without a SF3B1 mutation—but with the characteristic chromosomal pattern—might harbor mutations in one of these genes." (PMID 31426461, 2019).
hematological cancers (2 papers, 2022). "A recent study showed that U2AF1 is a haplo-essential oncogene for mouse hematopoietic cancer cell survival and U2AF1 mutations are always heterozygous with the residual WT allele." (PMID 36139566, 2022). "Especially, applications where detection of U2AF1 mutations is critical, including sequencing of hematological cancers or studies of spliceosome dysfunction." (PMID 35041928, 2022).
blood cancers (1 paper, 2022). "Previous studies reported that disrupted splicing due to SF3B1 or U2AF1 mutation involves hematopoietic malignancy, HM, and heme biosynthesis in MDS or other blood cancers." (PMID 35085775, 2022).
lung (1 paper, 2024). "A subset of lung ADC primary samples have been reported to have “quasi-WT” status, which represents tumors with low S34F:WT mRNA ratios, but unchanged absolute U2AF1S34F or total U2AF1 mRNA levels." (PMID 39314447, 2024).
U2AF1 also shares sentences with these, for which no sentence is quoted: myeloproliferative neoplasm (9 papers); uveal melanoma (5); Down syndrome (2); essential thrombocythemia (2); infection (2); prostate carcinoma (2); refractory anemia (2); aplastic anemia (1); cervical cancer (1); cholangiocarcinoma (1); chronic neutrophilic leukemia (1); Cognitive Deficits (1); colon cancer (1); colorectal cancer (1); dysplasia (1); endometrial carcinoma (1); esophageal cancer (1); hairy cell leukaemia (1); head and neck cancer (1); leukocytosis (1); lymphoma (1); lymphoproliferative disorders (1); metastatic tumors (1); ovarian carcinoma (1); overlap syndromes (1); pancreatic adenocarcinoma (1); pineal germinomas (1); polycythemia vera (1); psoriasis (1); refractory anemia with ringed sideroblasts (1).
A further 4 diseases each share a sentence with U2AF1 in 1 paper.